FBXW7 (F-box and WD repeat domain containing 7)
Diseases named in the same sentence as FBXW7 in open-access papers (continued):
Sharing a sentence is not in itself a finding about the gene and the disease.
Hyperglycemia (3 papers, 2020 to 2022). An increased concentration of glucose in the blood. "In this study, Ephx2, Stc2, Cep19, Il15 and Fbxw7 genes were found to be associated with impaired glucose tolerance and hyperglycemia." (PMID 32095365, 2020). "Thus, the significantly downregulated Stc2, Il15, and Fbxw7 might associate with hyperglycemia and impaired glucose tolerance in GK rats at 3 and 4 weeks of age." (PMID 32095365, 2020). "The TR-hnRNPA2B1 complex has been reported to repress proliferation, migration, and tube formation of HRECs in hyperglycemia through the STAT-4/miR-223-3p/FBXW7 signaling pathway." (PMID 35308095, 2022). "Consistently, the down‐regulation of FBXW7 has been detected in DR samples and hRECs in hyperglycaemia." (PMID 33369138, 2021).
inflammatory bowel disease (3 papers, 2020 to 2025). A spectrum of small and large bowel inflammatory diseases of unknown etiology. "Another approach involves targeting upstream regulators of CCL2: F-box and WD repeat domain-containing protein 7 (FBXW7), an E3 ubiquitin ligase in the gut, promotes Ccl2 and Ccl7 expression, exacerbating inflammatory bowel diseases (IBDs)." (PMID 40867747, 2025). "Previous studies suggested that the F-box and WD repeat domain-containing 7 (FBW7), as a substrate receptor (SR) of SKP1–Cul1–F-box (SCF), was predominantly upregulated in the colon tissues of patients with inflammatory bowel disease (IBD) and was correlated with its severity." (PMID 37006236, 2023).
Intellectual disability (3 papers, 2019 to 2025). "A particularly interesting fact is that the child exhibited intellectual disability combined with hemangioma due to mutation in the FBXW7 gene, which heretofore has not been reported." (PMID 39364007, 2024).
Intestinal tumours (3 papers, 2013 to 2022). "Reportedly, that FBXW7 regulates the biology of intestinal tumors by regulating the abundance of different substrates in a dose-dependent manner." (PMID 36159747, 2022). "FBXW7 haploinsufficiency fails to antagonize the Notch activity in human intestinal tumors." (PMID 36159747, 2022).
liver fibrosis (3 papers, 2020 to 2023). "Importantly, like FBXW7, PPARA expression declines as NASH progresses and is significantly reduced in liver fibrosis, cirrhosis, and HCC, with low PPARA expression associated with a poor survival rate among HCC patients." (PMID 37914694, 2023). "Recently, FBXW7 has been shown to degrade ZFP36 to regulate sorafenib-induced ferroptosis, revealing that ferroptosis is a therapeutic target for liver fibrosis." (PMID 34869326, 2021).
myeloma (3 papers, 2013 to 2025). "On the contrary, forced expression of miR-27b-3p inhibitors in myeloma fibroblasts inhibits the level of miR-27b-3p and induces a significant increase in the concomitant increase of FBXW7 mRNAs and protein." (PMID 36998461, 2023). "Clinical data shows that the expression of miR-32 is increased in multiple myeloma (MM) tissues, and cells with high expression of miR-32 are often accompanied by low expression of FBXW7." (PMID 36998461, 2023). "Overexpression of miR-27b-3p mimics in myeloma fibroblasts significantly inhibits FBXW7 mRNAs and protein." (PMID 36998461, 2023). "Interestingly, the list includes the gene SLC31A2 a membrane pump involved in resistance to alkylating drugs; FBXW7, USP6, UBE2J1 and Wnt-5a involved in ubiquitin proteasome pathways known to affect myeloma biology." (PMID 24376673, 2013).
nasopharyngeal carcinoma (3 papers, 2016 to 2025). A carcinoma arising from the nasopharyngeal epithelium. "The regulation between FBXW7 and VEGFA was also confirmed in nasopharyngeal carcinoma." (PMID 36991467, 2023).
uterine cancer (3 papers, 2021 to 2025). Primary or metastatic malignant neoplasm involving the uterine corpus and/or the cervix. "Despite the frequent occurrence of FBXW7 mutations in EC and the pathogenicity of Fbxw7 deletion in a genetically engineered mouse model of uterine cancer, little is known regarding the functional consequences of FBXW7 mutations in the context of human EC cells." (PMID 40087851, 2025). "Similarly, the three F-box protein genes typically harbor few mutations, (1–20 total mutations) within most cancer types (right); however, FBXW7 is the most frequently mutated gene with 107 and 117 cases in colorectal and uterine cancers, respectively." (PMID 35008511, 2021).
uterine carcinosarcoma (3 papers, 2020 to 2022). A usually aggressive malignant neoplasm arising from the uterine corpus and less often the cervix. "A reported mouse model of uterine Fbxw7 and Pten loss developed invasive endometrioid intraepithelial neoplasia followed by uterine carcinosarcomas at late stage confirmed as endometrial epithelial origin." (PMID 34941867, 2021).
uterine serous carcinoma (3 papers, 2019 to 2024). "FBXW7, a known tumor suppressor gene previously identified in uterine serous carcinoma, was detected in two cases." (PMID 39239274, 2024). "Additionally, alterations in FBXW7 and CCNE1, both involved in cell cycle regulation, have been found in 20% of uterine serous carcinomas." (PMID 39421446, 2024).
vulvar carcinoma (3 papers, 2014 to 2023). "Variants in several genes, including FBXW7 (4%), have been identified in a vulvar cancer cohort using targeted hot-spot sequencing, along with specific protein changes for targetable genes." (PMID 37408248, 2023). "FBXW7 has also been shown to be mutated in uterine carcinosarcoma (UCS) and vulvar cancer, both of which are rare gynecological malignancies." (PMID 37408248, 2023).
adenoid cystic carcinoma (2 papers, 2015 to 2024). A malignant tumor arising from the epithelial cells. "Among other salivary gland neoplasms, genomic alterations in FBXW7, KLHL6, and LRP1B have been identified in adenoid cystic carcinoma." (PMID 26634163, 2015).
atherosclerosis (2 papers, 2024 to 2025). A disease characterized by the build-up of fatty material and calcium deposition in the arterial wall resulting in partial or complete occlusion of the arterial lumen. "In atherosclerosis, ubiquitination of mTORC1 components by E3 ligases such as FBXW7 has been shown to regulate macrophage apoptosis, influencing plaque stability." (PMID 40734978, 2025).
bladder tumor (2 papers, 2012 to 2020). "Thus, we performed the mutation analysis of FBXW7 gene in 18 prostate, 24 kidney, and 16 bladder tumor tissues from Chinese patients." (PMID 23166673, 2012).
Clear Cell Renal Cell Carcinoma (2 papers, 2022 to 2026). "In clear cell renal cell carcinoma, ACLY expression is upregulated through HIF-2α/LPCAT1/FBXW7 and VHL/PPARγ axes, promoting lipid synthesis, tumor proliferation, and metastasis." (PMID 41958067, 2026).
colorectal adenoma (2 papers, 2013 to 2019). An adenoma that arises from the colon or rectum. "We identified genes with somatic mutations in the normal-colorectal adenoma samples, APC, CTNNB1, LRP5, FBXW7, and ATM, which overlapped with the TCGA data." (PMID 31336886, 2019).
COVID-19 (2 papers, 2022 to 2023). A disease caused by infection with severe acute respiratory syndrome coronavirus 2. "Specifically, several Notch-related genes were upregulated in COVID-19 samples for all three organs, including HDAC9, a selective regulator of Notch, FBXW7, a regulator of angiogenesis through Notch, and TBLR1, an indirect Notch regulator through degradation." (PMID 37830426, 2023). "Interestingly, two of these genes, FBXW7 and BNIP3, determine the cell fate via autophagy of mitochondria and apoptosis, implying the important role of mitochondrial functions in COVID-19 severity." (PMID 35547187, 2022).
depression (2 papers, 2022). "Therefore, the present research focuses on the role of β-arrestin-1, FBXW7, CD17, copper, zinc, calcium, and magnesium in depression/anxiety due to T2DM." (PMID 35055338, 2022).
dyslipidemia (2 papers, 2019 to 2022). "Furthermore, this study was the first to discover that several CpG sites in genes involved in lipid metabolism (AMFR, FBXW7, INSIG1/2, MBTPS2) are associated with dyslipidemia." (PMID 36570009, 2022).
dysplasia (2 papers, 2017 to 2022). A usually neoplastic transformation of the cell, associated with altered architectural tissue patterns. "Intestinal metaplasia (P = 0.013) and dysplasia (P = 0.036) were more severe in Fbxw7+/− mice than in Fbxw7+/+ mice." (PMID 28422719, 2017). "In contrast, mutations in JAK3 (Janus kinase 3), MET, and FBXW7 (F-Box and WD repeat domain containing 7) were found only in non-progressing dysplasia, but absent in progressing dysplasia and LSCC cases." (PMID 35406495, 2022).
heart failure (2 papers, 2011 to 2022). Inability of the heart to pump blood at an adequate rate to meet tissue metabolic requirements. "Analysis of the leucocyte transcriptome in 294 patients without overt heart failure revealed that levels of FECH, TMEM79, FBXW7, NGFB, ALK, UBN1, and SLC43A2 in peripheral blood were able to predict ALVD with 87% accuracy and 100% precision." (PMID 35722087, 2022). "UBN1, NGF and FECH genes displayed similar statistically significant regulation (up or down regulated) in hearts samples from heart failure patients but expression of the three remaining genes (TMEM79, FBXW7 and SLC43A2) could not be quantified, probably because of their low expression in heart." (PMID 21731613, 2011).
liposarcoma (2 papers, 2018 to 2024). A usually painless malignant tumor that arises from adipose tissue. "In a previous large-scale genomic sequencing study of soft tissue sarcoma specimens, that included 50 DD liposarcomas, a different CTNNB1 (T41I) mutation was described in a DD liposarcoma, including 3 other nonrecurring mutations (CDH1 (N238D), EPHA1 (A2127) and FBXW7 (E113fs))." (PMID 29731991, 2018).
male infertility (2 papers, 2024). The inability of the male to effect fertilization of an ovum after a specified period of unprotected intercourse. "Deletion of FBXW7 in germ cells suppresses differentiation by upregulation of MYC and CCNE1 and leads to male infertility, which is similar to the phenotype of Cwf19l2‐SKO mice in this study." (PMID 38889293, 2024).
mediastinal lymphoma (2 papers, 2020 to 2022). "Of the 16 loss-of-function SNVs that were identified, the most notable was that of a potential cause for early onset feline mediastinal lymphoma, with a stop gain in tumour suppressor gene FBXW7 (found in one cat and its offspring)." (PMID 36288160, 2022). "Focusing specifically on potentially rare variants with high impacts in constrained genes identified a potential cause for early onset feline mediastinal lymphoma, a stop gain in tumor suppressor gene FBXW7." (PMID 33090996, 2020). "Of the four SNVs consistent across both annotation sources and in cats segregating for disease, the most notable is a stop gain in the tumor suppressor F-box and WD repeat domain containing 7 (FBXW7), which was only found in a parent and child segregating for feline mediastinal lymphoma." (PMID 33090996, 2020).
Merkel cell carcinoma (2 papers, 2016 to 2019). "Importantly, aberrations in the PI3K/AKT/mTOR pathway (AKT2, FBXW7, NF1, PIK3CA, PIK3R1, PTEN or RICTOR) were also commonly seen in Merkel cell carcinomas (9/17 [53%])." (PMID 26981779, 2016).
myocardial infarction (2 papers, 2021 to 2023). Gross necrosis of the myocardium, as a result of interruption of the blood supply to the area, as in coronary thrombosis. "In recent years, a lot of work has found that miR-223-3p targets FBXW7 to regulate myocardial inflammation and apoptosis after myocardial infarction." (PMID 36660176, 2023).
non-alcoholic fatty liver disease (2 papers, 2015 to 2020). "The FBXW7-SREBF axis has been proposed in mouse models of non-alcoholic fatty liver disease." (PMID 26575021, 2015).
osteoarthritis (2 papers, 2022 to 2023). A noninflammatory degenerative joint disease occurring chiefly in older persons, characterized by degeneration of the articular cartilage, hypertrophy of bone at the margins and changes in the synovial membrane. "On the contrary, overexpression of FBXW7 by intra-articular injection of adenovirus restrained osteoarthritis in mice." (PMID 37359559, 2023). "Most recently, an outstanding study showed that downregulating FBXW7 promotes chondrocyte senescence and osteoarthritis development." (PMID 36104351, 2022). "A recent outstanding study reported that downregulating FBXW7 promotes chondrocyte senescence and osteoarthritis development upon mechanical overloading by targeting MKK7 for degradation, which consequently stimulates the JNK signaling." (PMID 36104351, 2022). "Depletion of FBXW7 in chondrocytes enhanced cartilage catabolism and caused chondrocyte senescence via promotion of p16, p21 and Colx and reduction of Col2a1 and ACAN, contributing to the exacerbation of osteoarthritis." (PMID 37359559, 2023). "In particular, lower expression of FBXW7 and higher expression of VEGF and HIF-1α were observed in osteoarthritis cartilage and IL-1β-mediated degenerated chondrocytes." (PMID 37359559, 2023).
pancreatic adenocarcinoma (2 papers, 2017 to 2022). "F-box and WD repeat domain-containing 7 (FBW7) have the ability to activate ferroptosis to strengthen the toxicity of gemcitabine-targeting pancreatic adenocarcinoma cells." (PMID 35517502, 2022).
polyp (2 papers, 2018 to 2022). A usually exophytic mass attached to the underlying tissue by a broad base or a thin stalk. "We compared mouse duodenal polyp- versus non-polyp-derived organoids (mPOs vs mNPOs), mutated for intestinal Apc and Fbxw7 tumour suppressor genes, with mPOs showing elevated lactate and consumption of glucose in the medium." (PMID 35046388, 2022).
rectal NETs (2 papers, 2023 to 2024). "Different miRNAs related to high mitotic indices or FBXW7 mutations may contribute to tumor behaviors in rectal NETs." (PMID 37047300, 2023). "hsa-miR-769-5p appears to be a possible regulator of FBXW7-mutated rectal NETs." (PMID 37047300, 2023). "Understanding the epigenetic regulation of FBXW7 in rectal NETs may provide insights into the mechanisms underlying tumor development and potentially identify novel therapeutic targets for treating these tumors." (PMID 37047300, 2023). "hsa-miR-3934-5p may be strongly implicated in a high mitotic index, which may eventually contribute to higher grade 2 tumors in rectal NETs, whereas hsa-miR-769-5p related to FBXW7 mutation may be involved in grade 1 tumors and is likely to play a role in suppressing rectal NET progression." (PMID 37047300, 2023). "In this study, screening 584 miRNA expressions in rectal NETs revealed that FBXW7 and mitotic index were the sole candidate genes and clinicopathological features specifically relevant to miRNAs, respectively." (PMID 37047300, 2023).
rectal tumors (2 papers, 2019 to 2024).
Sepsis (2 papers, 2020 to 2023). Sepsis is defined as life-threatening organ dysfunction caused by a dysregulated host response to infection. "CaMKIV signaling mediated the autophagic response to sepsis-induced AKI, by inhibiting GSK3β and FBXW7 expression and maintaining mTOR." (PMID 37215112, 2023).
thyroid cancer (2 papers, 2019 to 2022). "In previous studies, BID, FBXW7, and GPX4 had already been found to be significant in thyroid cancer, whereas the role of AKR1C3 and MAP3K5 in the development and progression of thyroid cancer has not yet been reported." (PMID 35741758, 2022). "AKR1C3, BID, FBXW7, GPX4, and MAP3K5 were independent prognosis signatures of thyroid cancer." (PMID 35741758, 2022).
type I diabetes (2 papers, 2021 to 2023). "The current study tried to uncover the molecular mechanism of E3 ubiquitin ligase F-box and WD repeat domain-containing 7 (FBW7) in a heritable autoimmune disease, type I diabetes (T1D)." (PMID 34802056, 2021).
adenomyosis (1 paper, 2025). The growth of endometrial tissue inside the muscular wall of the uterine corpus. "In adenomyosis, the most frequently mutated genes included KRAS (34.1%), PIK3CA (12.2%), ARID1A (12.1%), and FBXW7 (9.8%)." (PMID 40679511, 2025). "Although mutations in FBXW7, ARHGAP35, PIK3R1, and PPP2R1A were also detected in adenomyosis, their frequencies were not higher than those in the normal endometrium." (PMID 40679511, 2025).
Cognitive impairment (1 paper, 2025). Abnormal cognition is characterized by deficits in thinking, reasoning, or remembering. "Moreover, we showed that overexpression of FBXW7 in the hippocampus attenuated cognitive deficits and tau pathologies in PS19 mice." (PMID 41311387, 2025).
endometrial stromal sarcoma (1 paper, 2022). "To this end, we generated the endometrial stromal sarcoma associated JAZF1-SUZ12 fusion and investigated how FBXW7 affects its protein level compared to intact JAZF1 and SUZ12." (PMID 35328741, 2022).
female infertility (1 paper, 2024). Diminished or absent ability of a female to achieve conception. "The mice with oocyte‐specific deletion of Fbxw7 gene demonstrated ovarian atrophy, follicle loss and ultimately female infertility." (PMID 39031722, 2024). "Our results establish the important role of Fbxw7 in folliculogenesis and ovarian function, and might provide valuable information for understanding POI and female infertility." (PMID 39031722, 2024). "We further showed that mice with oocyte‐specific deletion of Fbxw7 demonstrated POI, characterized with folliculogenic defects, early depletion of follicle reserve, disordered hormonal secretion, ovarian dysfunction and female infertility." (PMID 39031722, 2024).
focal segmental glomerulosclerosis (1 paper, 2015). A renal disorder characterized by sclerotic lesions in the glomeruli. "We detected by aCGH the first case of germline deletion confined to the FBXW7 gene in a patient with a syndromic phenotype characterized by small stature, relative-to-height macrocephaly, focal segmental glomerulosclerosis (FSGS) and multiple, early/atypical onset primitive tumors." (PMID 26482194, 2015).